DOT1L (DOT1 like histone lysine methyltransferase)
Diseases named in the same sentence as DOT1L in open-access papers (continued):
Sharing a sentence is not in itself a finding about the gene and the disease.
cancer (continued). "DOT1L has been identified to be a drug target for several other types of cancers." (PMID 27316347, 2016). "The development of DOT1L inhibitors is a hot area in anti-cancer drug research." (PMID 27531902, 2016). "Firstly, Dot1l mediated methylation of H3K79 has been implicated in transcriptional elongation and cell cycle regulation, which influence the cell division and differentiation and then generate cancer cells." (PMID 27713173, 2016). "However, whether ECM stiffness modulates DOT1L activity in UM, thereby affecting cancer stemness, is yet to be elucidated." (PMID 41533929, 2025). "However, we know from studies on cancer cells that DOT1L has many interaction partners." (PMID 38962004, 2024). "Additionally, in the TNBC cell line MDA-MB-231, pharmacologic HDAC inhibition with trichostatin A-induced re-expression of Snail, ZEB1, and ZEB2 transcription factors in DOT1L-knockdown cells reinforced the EMT and cancer stem cell-promoting function of p300 in the presence of DOT1L." (PMID 37568822, 2023). "Furthermore, DOT1L and H3K79 methylation were found to be essential for ionizing radiation (IR)-induced 53BP1 foci formation during G1/G2 phase, and DOT1L depletion in cancer cells led to prolonged presence of phosphorylated histone H2AX on Ser139 (γH2AX) post-IR, suggestive of defective DNA repair." (PMID 34887387, 2021). "Notably, 190 out of 2121 DOT1L target genes were included in the Cancer Gene Census (CGC)." (PMID 32698374, 2020). "Furthermore, the introduction of an N6-methyl group into F-NepA reduced the cancer cell antiproliferative activity of this analog and the DOT1L-mediated suppression of H3K79me2, indicating that the N6-amine moiety is a pivotal structural chemical component in the bioactivity of NepA analogs." (PMID 32244385, 2020). "However, in ovarian cancer, DOT1L inhibits cell invasion and cancer stem-like cell property." (PMID 31888761, 2019). "In addition to cancer, DOT1L was recently found to play a role in cell reprogramming." (PMID 27316347, 2016). "In addition, Dot1l has some other regulatory functions, which may have something to do with cancer, such as inhibition of somatic reprogramming and promotion in DNA damage repair." (PMID 27713173, 2016). "These include FLT3 in FLT3-ITD positive cells, DOT1L in PICALM-MLLT10, and the oncogene c-MYC, which is overactive in most cancer types." (PMID 40082888, 2025). "CDK1 has been shown to phosphorylate and regulate distinct functions of several substrates, including disruptor of telomeric silencing 1-like (DOT1L), SRY-box transcription factor 2 (SOX2), and pyruvate dehydrogenase kinase 1 (PDK1), in various cancers." (PMID 40695806, 2025). "We show that DOT1L inhibition promotes DNA damage and activates an interferon (IFN) response in ER-positive breast cancer cells as well as in HER2-positive cancer cells." (PMID 41299712, 2025). "This stabilization enables DOT1L to catalyze H3K79 methylation of genes involved in EMT, promoting cancer metastasis and invasion." (PMID 39394462, 2024). "It quickly became clear that the aberrant recruitment and targeting of DOT1L and the resultant skewing of H3K79 methylation patterns across the epigenome were the major drivers of oncogenesis in this type of cancer." (PMID 38962004, 2024). "Thus, hesperetin targeting DOT1L may translate into future cancer treatment strategies." (PMID 37179342, 2023). "Moreover, the mutational status of the cell lines used in this study need to be considered and further validations of DOT1L and menin inhibitors on patient-derived OC models and xenografts are necessary to confirm the beneficial effect of the drug combination in clinically relevant cancer models." (PMID 36333801, 2022). "In fact, targeting DOT1L by pharmacological interventions inhibited the growth and metastasis of TNBC cancer." (PMID 36185256, 2022).
cancer (continued). "Currently, several histone modification regulators, including DOT1L, DNMT1, EZH2, and KDM5B, have been reported to play a role in the TGFβ-stimulated ZEB2 transcriptional upregulation of many cancers." (PMID 35606881, 2022). "Some selective inhibitors of specific protein methyltransferases, including DOT1L, EZH2 and PRMT5, are currently under clinical investigation as cancer therapeutics." (PMID 33778494, 2021). "Background and Aim: DOT1L regulates various genes involved in cancer onset and progression by catalyzing H3K79 methylation, but how DOT1L activity itself is regulated is unclear." (PMID 32042335, 2020). "DOT1L pharmacologic inhibition induces AML cell differentiation and modulates the expression of genes with relevant roles in cancer development." (PMID 32698374, 2020). "To reveal the function of DOT1L in CRC, we firstly compared the expression of DOT1L in CRC and other types of cancers in Bittner multi-cancer datasheet from the Oncomine." (PMID 31888761, 2019). "The MLL1‐ZC3H13 chimera consistently increased the expression of a cancer stem cell marker (CD44); in addition, we detected potential collateral lethality between DOT1L and MLL1 fusions." (PMID 30548174, 2019). "Significant differentiation effects were detected for Menin-MLL, DOT1L, and DHODH inhibitors, whereas BET and CDK9 inhibitors primarily induced apoptosis in AML/ALL cancer models." (PMID 31253180, 2019). "The histone methyltransferases DOT1L and EZH2, as well as the demethylase LSD1, are three promising histone methyltransferases and demethylases in clinical trials for cancer therapy." (PMID 31888761, 2019). "Among the targets in our chemical probe collection, several have agents currently in clinical trials for cancer (EZH2, EED, DOT1L, PRMT1, and PRMT5) and additional PMT inhibitors are in preclinical studies." (PMID 30604761, 2019). "This is an important point since inhibition of chromatin regulators such as EZH2, DOT1L and LSD1, which also exist in stable multi-protein complexes is currently under clinical investigation in several cancers." (PMID 30431433, 2018). "The DOT1L complex induces the core stem cell genes NANOG, SOX2 and Pou5F1, thereby resulting in increased cancer stemness and tumorigenic potential." (PMID 25590298, 2015). "IL-22 in cancer cells can promote activation of the transcription factor STAT3 and expression of the histone 3 lysine 79 (H3K79) methyltransferase DOT1L." (PMID 25590298, 2015). "These interactions are at the basis of DOT1L involvement in cancer development, as in some types of mixed lineage leukemia in which the fusion between MLL1 protein and DOT1L partners (such as ENL, AF9, or AF10) leads to the ectopic activation of MLL1 target genes by DOT1L11–13." (PMID 39875559, 2025). "Thus, epigenetic regulators have served as potential targets for cancer therapy, and several drugs have been approved or are currently undergoing clinical trials by the FDA, including inhibitors against DOT1L/KMT4." (PMID 38778348, 2024). "We suspect that DOT1L may affect WNT signaling by influencing expression of CTNNB1 and promote the formation of cancer stem cells by promoting CD44 expression." (PMID 38495505, 2024). "Whilst these trials have shown promise for DOT1L inhibition as a cancer therapeutic, they have also highlighted the current lack of understanding regarding the contribution of DOT1L to normal homeostatic biology, such as within the immune system." (PMID 38962004, 2024). "Treatment with the promising DOT1L inhibitor EPZ-5676 stopped the growth of GBM stem cells without effecting non-GBM cancer cell lines." (PMID 39765675, 2024). "It was further established, via a suite of laboratory testing, that DOT1L inhibition resulted in dysregulation of the cell cycle and cell death in MLL-fusion-driven leukemic cells as well as resensitisation to chemotherapy in other types of cancer." (PMID 38962004, 2024).
cancer (continued). "DOT1L, EZH2, and LSD1 inhibitors are currently being evaluated in clinical trials with evidence of therapeutic activity, underscoring their promise as anti-cancer agents." (PMID 35710782, 2022). "Moreover, combination therapy with DOT1L and SHP2 inhibitors was demonstrated to be effective in treating a specific subset of KRAS-mutant cancers characterized by a very poor prognosis." (PMID 35495127, 2022). "Due to the large number of these proteins, only those highly relevant to cancer are described, with a particular focus on histone H3 lysine 79 (H3K79) methyltransferase DOT1L, H3K4 targeting mixed lineage leukemia (MLL) and lysine-specific demethylase 1 (LSD1), and H3K27 methyltransferase EZH2." (PMID 27316347, 2016). "The positive correlations of DOT1L with BCAT1 (Pearson correlation γ was 0.5202; p < 0.01) and LDHA with BCAT1 (Pearson correlation γ was 0.5202; p < 0.01) were analyzed from gene expression profiles of 549 GBM cases of the Cancer Genome Atlas (TCGA) database, respectively." (PMID 37298317, 2023). "Coupled to a significant DOT1L specificity in comparison with other lysine methyltransferases, EPZ004777 showed a surprising ability to selectively inhibit proliferation of MLL-rearranged cells, decreasing H3K79 methylation level and inducing a profound transcriptome deregulation of cancer cells." (PMID 35495127, 2022). "Taken together, these results indicate that DOT1L has biological functions that are independent of H3K79 methylation, and degrading DOT1L instead of solely inhibiting its catalytic activities might be more important for cancer treatments." (PMID 35331314, 2022). "Moreover, noncanonical DOT1L inhibitors such as psammaplin A analogues induced similar effects in Triple-negative breast cancer cells by inhibition of cancer cell proliferation and metastasis." (PMID 35495127, 2022). "Thus, disrupting transcription elongation using DOT1L inhibition or when combined with other transcription inhibitors, such as BETi JQ1, could trigger R-loops and genome instability in cancer cells." (PMID 33498525, 2021). "We first examined CBP protein and DOT1L(K358) acetylation levels in the human tissue arrays and found that the CBP expression in CRC tissues was significantly higher than in the corresponding cancer-adjacent normal tissues and positive correlates with CRC progression." (PMID 32042335, 2020). "Inhibitors targeting the histone methyltransferases DOT1L and EZH2, as well as the demethylase KDM1 (also known as LSD1), have recently entered the first stages of clinical trials in cancer therapy and might hold the potential to modulate the cancer-immune system axis." (PMID 28545238, 2017). "Since cancer metastasis is a multistep process including cell migration and invasion, we determined whether F-NepA is able to regulate the metastatic potential of human TNBC cells via the inhibition of these two processes which might be coincident with DOT1L expression." (PMID 32244385, 2020). "During pharmacological screens in the Cancer Cell Line Encyclopedia (CCLE), we noticed a modest growth inhibitory effect of DOT1L inhibitors on MM cell lines (data not shown)." (PMID 32215184, 2020). "It is noted that, similar to many epigenetic inhibitors (e.g., DOT1L or LSD1 inhibitors 25, 37, 38), compound 1 did not significantly inhibit proliferation of sensitive cancer cells during the first 2-3 days, while it showed potent activity upon incubation for more than 5 days." (PMID 34373735, 2021). "In addition, inhibitors targeting the histone methyltransferase DOT1L and the demethylase LSD1 are being explored for their therapeutic potential, as they can modify the epigenetic landscape of cancer cells and influence gene expression without disrupting the DNA sequence." (PMID 41431699, 2025).
tumor (70 papers, 2011 to 2026). "DOT1L loss cooperated with LSD1 inhibitors to activate tumor suppressive programs, while pharmacologic inhibition of DOT1Ls catalytic activity failed to elicit comparable effects." (PMID 40781484, 2025). "To unravel the mechanism underlying the anti-tumor effect of DOT1L inhibition, we performed a gene expression microarray analysis with MCF7 and SKBR3 cells treated with a DOT1L inhibitor for 6 days." (PMID 41299712, 2025). "It was found that the global levels of H3K79 dimethylation (H3K79me2) were abnormally increased in IDH1/2-mutated tumor cells due to the overexpression of DOT1L." (PMID 34425876, 2021). "Loss of one copy of Dot1L increased survival rate and tumor latency (48% incidence, comparison to Hdac1f/f alone P = 0.002)." (PMID 31304633, 2019). "Examination of xenograft tumor volumes and weight indicated that loss of DOT1L promoted xenograft formation." (PMID 29343685, 2018). "Therefore, loss of DOT1L from a subset of LSD1-bound enhancers seems to be required for potent induction of a network of tumor suppressive genes under Bomedemstat treatment." (PMID 40781484, 2025). "In particular, the enzymes controlling the main histone marks, known as epigenetic “writers” (e.g., DOT1L) and ‘”erasers,” together with the epigenetic “readers” are able to modulate the transcriptional programs underlying breast carcinogenesis, tumor growth, and progression." (PMID 35495127, 2022). "It appears that treating IDH mutated tumor with DOT1L inhibitor may also be a feasible strategy for AML." (PMID 34425876, 2021). "Furthermore, expression of four proteins is associated with tumor progression/high risk AML: DOT1L, mTOR, VIM and ZNF521, whereas the expression of six proteins is associated with tumor suppression/low risk AML: AEBP2, CAST, CBFB, LSP1, MAP1S and probably PCBP1." (PMID 30634713, 2019). "In addition, suppression of DOT1L expression causes a reduction of tumor cell growth." (PMID 31293964, 2019). "Inhibiting DOT1L impairs PC tumor growth and colony formation by suppressing AR and MYC signaling in preclinical models." (PMID 41601922, 2026). "The results summarized above suggest that DOT1L inhibition exerts its anti-tumor effect in MCF7 cells by inhibiting estrogen signaling and inducing IFN signaling." (PMID 41299712, 2025). "Inhibition of PIEZO1 or DOT1L diminished stemness properties and tumor growth both in vitro and in vivo." (PMID 41533929, 2025). "Knockout of STING1 attenuated the induction of IRGs as well as the anti-tumor effect of DOT1L inhibition in MM cells." (PMID 41299712, 2025). "In this study, we demonstrated that DOT1L is an independent prognosticator for patients with ovarian high-grade serous carcinoma, exhibiting cellular functions of a tumor promoter." (PMID 38778348, 2024). "According to the TCGA and GTEx datasets, the expression for DOT1L within 375 tumour individuals were substantially in excess of within 391 healthy individuals." (PMID 38495505, 2024). "The TCGA database showed that the expression for DOT1L within 375 tumour individuals remained substantially greater compared to that within 32 normal controls." (PMID 38495505, 2024). "High mRNA expression of both EZH2 and DOT1L in NB tumour samples correlated with the poorest patient survival." (PMID 39501501, 2024). "Following 1 month of continuous treatment, the size, volume, and weight of transplanted tumors in DOT1L knockdown mice were found to be noticeably reduced by measuring the tumor volume and weight." (PMID 38910244, 2024). "It is unclear how DOT1L contributes to the survival of tumor-initiating or solid stem cell-like cells in tumors." (PMID 38495505, 2024).
tumor (continued). "In leukemia and solid tumors, DOT1L has been shown to have the cellular function of a tumor-promoter." (PMID 38778348, 2024). "The expression of EZH2 and DOT1L were further assessed for correlations across patient tumours from the two large databases." (PMID 39501501, 2024). "Decreased methionine levels severely impact DOT1L-mediated H3K79me in tumour infiltrating lymphocytes (TILs), leading to decreased STAT5 expression." (PMID 38962004, 2024). "High intraperitoneal (IP) bioavailability and clearance of this molecule in animal models represented a fundamental improvement toward the clinical use of DOT1L inhibitors and induced a significant tumor regression in xenograft mice." (PMID 35495127, 2022). "Decreased DOT1L along with low levels of H3K79me3 is associated with epithelial–mesenchymal transition (EMT) and PDL1 expression, but the effect of DOT1L on tumor immunity is still under investigation." (PMID 36048239, 2022). "In the mammary gland, DOT1L promotes multistep carcinogenesis, as its expression is required for the malignant transformation of breast epithelial cells and for tumor initiation." (PMID 35495127, 2022). "Recently, several studies explored the activity of the histone methyltransferase DOT1L in GI cancers, elucidating its role in tumor growth and response to current treatments." (PMID 35495127, 2022). "Further analysis revealed that the observed beneficial effect was associated with DOT1L blockade-induced upregulation of PREX1, which in turn activated MAPK signaling and enhanced vulnerability of tumor cells to SHP2 inhibition." (PMID 35495127, 2022). "In another study, genetic knockdown of DOT1L, or its pharmacological inhibition by specific inhibitors, was found to significantly impair survival and the tumor-forming potential of multiple OC cell lines both in vitro and in vivo." (PMID 35495127, 2022). "Combined, these findings enforce the idea of a possible targeting of DOT1L with selective molecules to treat neoplasms of the gastrointestinal tract." (PMID 35495127, 2022). "Simultaneously, the inhibition of DOT1L by DOT1L specific small interfering RNAs (siRNAs) reduced the invasion of the tumor and increased chemosensitivity." (PMID 34051847, 2021). "Remarkably, we found that DOT1L(K358) acetylation levels positively correlated with the histological tumor grade, suggesting that DOT1L(K358) acetylation levels progressively increase during CRC progression." (PMID 32042335, 2020). "PsA-3091, a heteromonomeric structured analog with a tertiary butyl functional group at the aromatic ring, showed the most effective and selective inhibition towards DOT1L activity, along with suppression of tumor growth and metastasis in TNBC cells." (PMID 33379275, 2020). "So far, only the DOT1L inhibitor EPZ-5676 has been demonstrated to achieve tumor regression in preclinical models." (PMID 32215184, 2020). "Consistently, we also found that CBP expression correlates with tumor stage and poor prognosis in CRC, further strengthening our data that CBP-mediated DOT1L acetylation at K358 has a vital role in tumor progression and prognosis." (PMID 32042335, 2020). "We next examined the correlation of DOT1L overexpression to tumor grade and outcome in PCa patients." (PMID 32814769, 2020). "In summary, we demonstrated that the histone methyltransferase DOT1L plays a key role in the regulation of tumor growth and metastasis in TNBC cells." (PMID 33379275, 2020). "Using DOT1L inhibitors and a knockdown approach, we established that DOT1L was required for survival of the tumor cells by preventing the induction of apoptosis, suggesting that DOT1L is required for tumor maintenance." (PMID 31304633, 2019). "c-Myc overexpression was used to rescue the cell cycle arrest and tumor growth induced by DOT1L silencing or inhibition in CRC." (PMID 31888761, 2019).